XRCC4 (X-ray repair cross complementing 4)
Description:
[DNA repair protein XRCC4]: DNA non-homologous end joining (NHEJ) core factor, required for double-strand break repair and V(D)J recombination. Acts as a scaffold protein that regulates recruitment of other proteins to DNA double-strand breaks (DSBs). Associates with NHEJ1/XLF to form alternating helical filaments that bridge DNA and act like a bandage, holding together the broken DNA until it is repaired. The XRCC4-NHEJ1/XLF subcomplex binds to the DNA fragments of a DSB in a highly diffusive manner and robustly bridges two independent DNA molecules, holding the broken DNA fragments in close proximity to one other. The mobility of the bridges ensures that the ends remain accessible for further processing by other repair factors. Plays a key role in the NHEJ ligation step of the broken DNA during DSB repair via direct interaction with DNA ligase IV (LIG4): the LIG4-XRCC4 subcomplex reseals the DNA breaks after the gap filling is completed. XRCC4 stabilizes LIG4, regulates its subcellular localization and enhances LIG4's joining activity. Binding of the LIG4-XRCC4 subcomplex to DNA ends is dependent on the assembly of the DNA-dependent protein kinase complex DNA-PK to these DNA ends. Promotes displacement of PNKP from processed strand break termini. [Protein XRCC4, C-terminus]: Acts as an activator of the phospholipid scramblase activity of XKR4. This form, which is generated upon caspase-3 (CASP3) cleavage, translocates into the cytoplasm and interacts with XKR4, thereby promoting phosphatidylserine scramblase activity of XKR4 and leading to phosphatidylserine exposure on apoptotic cell surface.
Synonyms: hXRCC4; SSMED
Tractability: Small molecule: a structure with a bound ligand is known; it has a high-quality binding pocket. PROTAC: UniProt records ubiquitination sites on it; ubiquitination databases record sites on it; its protein half-life has been measured.
Gene: Protein-coding gene on chromosome 5 (83,077,498 to 83,353,787, forward strand). Ensembl gene ENSG00000152422.
Subcellular location: Nucleus; Chromosome; Cytoplasm (Protein XRCC4, C-terminus)
Subcellular location (Human Protein Atlas): Nucleoplasm
Pathways (Reactome):
DNA Repair: Nonhomologous End-Joining (NHEJ)
Disease: 2-LTR circle formation
Metabolism of proteins: SUMOylation of DNA damage response and repair proteins
Gene Ontology:
Molecular function: DNA binding; enzyme binding; FHA domain binding; identical protein binding; ligase activity; protein binding; protein-macromolecule adaptor activity
Biological process: base-excision repair; DNA double-strand break attachment to nuclear envelope; double-strand break repair; double-strand break repair via nonhomologous end joining; positive regulation of ligase activity; protein localization to site of double-strand break; response to X-ray; immunoglobulin V(D)J recombination; DNA recombination
Cellular component: chromosome; condensed chromosome; cytoplasm; cytosol; DNA ligase IV complex; DNA-dependent protein kinase-DNA ligase 4 complex; nonhomologous end joining complex; nucleoplasm; nucleus; site of double-strand break
Genetic constraint (gnomAD): Loss-of-function variants: 27 observed, 36.06 expected, observed/expected ratio (o/e) 0.75, 90% interval 0.55 to 1.03. The upper end of that interval is the gene's LOEUF score, 1.03, which puts it in group 4 of 6, group 1 being the genes least tolerant of losing a copy. Missense variants: 340 observed, 380.85 expected, observed/expected ratio (o/e) 0.89, 90% interval 0.82 to 0.98. Synonymous variants: 117 observed, 126.75 expected, observed/expected ratio (o/e) 0.92, 90% interval 0.79 to 1.08.
Gene-disease validity (ClinGen):
ClinGen rates the evidence that XRCC4 causes each of these diseases.
hereditary nonpolyposis colon cancer (autosomal dominant): Limited.
Homologues: Orthologues: chimpanzee XRCC4 (99% identical), macaque XRCC4 (95% identical), rabbit XRCC4 (77% identical), guinea pig XRCC4 (75% identical), mouse Xrcc4 (74% identical), dog XRCC4 (72% identical), rat Xrcc4 (70% identical), tropical clawed frog xrcc4 (46% identical).
Diseases named in the same sentence as XRCC4 in open-access papers:
XRCC4 is named in the same sentence as 103 diseases in open-access papers, as found by Europe PMC text mining. Sharing a sentence is not in itself a finding about the gene and the disease. The quoted sentences say what the papers report.
breast carcinoma (25 papers, 2005 to 2026). "Carriers of the XRCC4 c.1394 G>T genotype were observed to have significantly higher risk of developing breast cancer compared to individuals with T/T genotype (OR=2.67, 95% CI: 1.36 – 5.25)." (PMID 31030479, 2019). "Significant difference in genotype (p=0.007) and allele (p=0.003) frequencies in XRCC4 c.1394G>T was observed between the breast cancer cases and controls." (PMID 31030479, 2019). "In the current study, the T/T variant of XRCC4 c.1394G>T was associated with reduced risk for breast cancer." (PMID 31030479, 2019). "This study shows that heterozygous G/T genotype of XRCC4 c.1394G>T is associated with breast cancer in selected Filipino population." (PMID 31030479, 2019). "Meta-analyses have shown the association of polymorphisms in XRCC4 gene specifically the G>T variant with increase in breast cancer risk among Asians and Caucasian, notably in Chinese, Korean, and American populations." (PMID 31030479, 2019). "Several studies have shown that some genetic variants of DNA repair genes, such as the X-ray cross-complementing group 4 (XRCC4) gene are associated with breast cancer pathogenesis." (PMID 31030479, 2019). "Consistent results from the two-stage genetic association study revealed that a recessive missense variant (rs3734091) of XRCC4 was significantly associated with an increased risk of non-BRCA1/2 breast cancer." (PMID 25360583, 2014). "In this two-stage case-control study with 1,764 non-BRCA1/2 breast cancer patients and 1,623 cancer-free controls, we investigated the contribution of genetic variants of XRCC4 to breast cancer susceptibility in Chinese women." (PMID 25360583, 2014). "In conclusion, we combined epidemiologic and experimental studies to establish a role for XRCC4 in the predisposition to non-BRCA1/2 breast cancer in a Chinese population." (PMID 25360583, 2014). "The current study identified XRCC4 as a non-BRCA1/2 breast cancer susceptibility gene in the Chinese population." (PMID 25360583, 2014). "We identified a missense variant (c.739G>T, p.Ala247Ser) of XRCC4 that correlated with an increased risk of non-BRCA1/2 breast cancer." (PMID 25360583, 2014). "Taken together, our findings document the role of XRCC4 in non-BRCA1/2 breast cancer predisposition and reveal its underlying biological mechanism of action." (PMID 25360583, 2014). "In this study, we have described haplotypes and characterized the LD structure of the ATM, MRE11A, and XRCC4 genes using a panel of 94 subjects, including breast cancer cases from high-risk breast cancer families as well as controls." (PMID 16091150, 2005). "The genes ATM, MRE11A, and XRCC4 were characterized using a panel of 94 unrelated female subjects (47 breast cancer cases, 47 controls) obtained from high-risk breast cancer families." (PMID 16091150, 2005). "Furthermore, the c.1394G>T SNP in XRCC4 is associated with the development of breast cancer in Filipinos." (PMID 37679817, 2023). "XRCC4 polymorphisms have also been linked to a risk of susceptibility for breast cancer." (PMID 30842344, 2019). "XRCC4 c.1394G>T combined with passive smoking may also significantly increase risk of breast cancer (OR=14.73; 95% CI= 9.88-18.86)." (PMID 31030479, 2019). "Hence, this study is the first to present the possible association of XRCC4 (c.1394G>T) polymorphism with the risk of breast cancer among Filipinos." (PMID 31030479, 2019). "Hence, this study was conducted to determine the association between XRCC4 c.1394G>T SNP and breast cancer development among Filipinos." (PMID 31030479, 2019). "The current study strongly suggested that the low and recessive population-specific genetic variant rs3734091 of XRCC4 may influence the risk of non-BRCA1/2 breast cancer, which could be missed by routine GWAS analyses of women of European ancestry." (PMID 25360583, 2014). "This work might implicate XRCC4 as a novel susceptibility locus for breast cancer risk evaluation and prevention." (PMID 25360583, 2014).
breast carcinoma (continued). "We identified a recessive missense variant, rs3734091 (c.739G>T, p.Ala247Ser), of XRCC4 that was significantly associated with an increased risk of breast cancer (odds ratio [OR] = 3.92, P = 0.007), particularly with the risk of developing triple-negative breast cancer (OR = 18.65, P < 0.0001)." (PMID 25360583, 2014). "Additionally, certain studies have reported that XRCC4 rs3734091 is involved in the susceptibility to other malignant tumors besides breast cancer, such as hepatic carcinoma and oral cancer." (PMID 25360583, 2014). "In addition, genotypic polymorphisms in NHEJ genes (XRCC4, Ligase IV and Ku 70) have been associated with increased risk to develop breast cancer or glioma." (PMID 19223975, 2009). "Moreover, cases who were exposed to passive smoking, whether carrying the XRCC4 G/T (OR=14.73, 95%CI 9.88-18.86) or T/T (OR=4.55, 95%CI 2.29-9.04) genotype, had increased risk for breast cancer." (PMID 31030479, 2019). "Subsequently, it was discovered that the overexpression of RUVBL1/DTL greatly increased the expression of NHEJ repair pathway molecules, namely K70, K80, DNA-PKcs, 53BP1, LIG4, and XRCC4, within breast cancer cells." (PMID 38609375, 2024). "In breast cancer, scoring XRCC4 expression using immunohistochemistry has proven to be effective in predicting postoperative breast cancer metastasis." (PMID 37679817, 2023). "Studies have found XRCC4 expression in various tumors, including uterine cervical cancer, breast cancer, esophageal cancer and hepatocellular carcinoma." (PMID 36765282, 2023). "In our study, we investigated the relationship between breast cancer risk and genetic variations in DNA repair [XRCC3 Thr241Met and XRCC4 G(‐1394) T] and apoptosis [BAX G(-248) A and BCL-2 C(‐938) A] pathways." (PMID 35320970, 2022). "Protein expression of PARP1, X-ray cross complementing protein 4/1 (XRCC4, XRCC1), and ERCC1 were risk factors for postoperative metastasis of breast cancer." (PMID 36612206, 2022). "We investigated the relationship between the risk of breast cancer and XRCC3 Thr241Met, XRCC4 G(-1394) T, BAX G(-248) A, and BCL2 C(-938) A gene polymorphisms." (PMID 35320970, 2022). "This study is aimed at determining the association of XRCC3 Thr241Met (rs861539), XRCC4 G(-1394) T (rs6869366) DNA repair and BAX G(-248) A (rs4645878), and BCL2 C(-938) A (rs2279115) apoptotic gene polymorphisms with breast cancer." (PMID 35320970, 2022). "The combined diagnosis of the PARR1, XRCC4 and ERCC1 have greater predictive value for the risk of metastasis of breast cancer (Se = 94.17%, Sp = 75.73%; OR 11.739, 95% CI 2.858 ~ 40.220, P < 0.05)." (PMID 33184404, 2020). "The predicted direction of association with contralateral breast cancer risk was uniformly increased for the LIG4, NHEJ1, and XRCC5 genes while uniformly decreased for the XRCC4 and XRCC6 genes." (PMID 31560388, 2019). "Results show that genotypic (p=0.007) and allelic (p=0.003) distribution pattern of XRCC4 c.1394G>T were significantly different between breast cancer cases and healthy controls." (PMID 31030479, 2019). "Genotyping for XRCC4 c.1394G>T SNP was performed on breast cancer patients (n=103) and their age- and sex- matched clinically healthy controls (n=103) by polymerase chain reaction – restriction fragment length polymorphism." (PMID 31030479, 2019). "As expected, endogenous XRCC4 showed a uniform nuclear staining pattern in breast cancer tissues with the rs3734091-GG and GT genotypes, whereas various XRCC4 distribution patterns appeared in breast cancer tissue sections with the XRCC4 rs3734091-TT genotype." (PMID 25360583, 2014). "In this study, we aimed to comprehensively evaluate the associations between XRCC4 genetic variants and non-BRCA1/2 breast cancer risk in a two-stage case-control study." (PMID 25360583, 2014).
breast carcinoma (continued). "For ATM, MRE11A, and XRCC4, we compared haplotypes and LD structure between the breast cancer cases and controls." (PMID 16091150, 2005). "In addition, the combined diagnosis of XRCC4, PARP1, and excision repair cross-complementation group 1 (ERCC1) has demonstrated considerable predictive capability in assessing the risk of breast cancer metastasis." (PMID 37679817, 2023). "Moreover, polymorphisms of XRCC4, another essential gene in the NHEJ pathway, were found to be associated with PR− breast cancer risk." (PMID 33734613, 2021). "In addition, the combined diagnosis of PARP1, XRCC4 and ERCC1 has great predictive value for the risk of breast cancer metastasis." (PMID 33184404, 2020). "Silencing of XRCC4 increased the radio-sensitivity of breast cancer cells." (PMID 32258128, 2020). "When XRCC4 or LIG4 were depleted in the EEPD1/RAD52 co-depleted BRCA1-deficient breast cancer cells, no significant reduction in cell survival was observed." (PMID 29145865, 2017). "In addition, an increase of ~ 30% in clonal cell survival was observed in the EEPD1/RAD52/XRCC4 triple-depleted breast cancer cells compared to the EEPD1/RAD52 co-depletion cells respectively." (PMID 29145865, 2017). "To determine whether a similar mutator phenotype was present at the tissue level, we performed IHC to evaluate endogenous XRCC4 expression in human mammary tumors with different rs3734091 genotypes." (PMID 25360583, 2014). "For ATM, MRE11A and XRCC4 we repeated the analysis in cases and controls separately to determine whether LD structure was consistent across breast cancer cases and controls." (PMID 16091150, 2005). "In protein expression, PARP1 (OR 1.147, 95% CI 1.067 ~ 1.233, P < 0.05), XRCC4 (OR 1.088, 95% CI 1.015 ~ 1.166, P < 0.05), XRCC1 (OR 1.114, 95% CI 1.021 ~ 1.215, P < 0.05), ERCC1 (OR 1.068, 95% CI 1.000 ~ 1.141, P < 0.10) were risk factors for postoperative metastasis of breast cancer." (PMID 33184404, 2020). "Notably, there have only been a few studies on the associations between genetic variants of XRCC4 and breast cancer susceptibility; these studies were performed regardless of the BRCA1/2 status, and the results were inconclusive." (PMID 25360583, 2014). "Previous studies have shown that, in breast cancer, the analysis of eight DNA repair-related genes, including RPA3 and XRCC4, among others, reveals that patients exhibiting high expression levels of these genes tend to have poorer prognoses." (PMID 40243892, 2025). "HMGB3, XRCC4, RGS3 and PFKL have been identified as potential target genes for breast cancer in many studies, providing more directions for the treatment of breast cancer patients." (PMID 39669558, 2024). "From two pairs of matched breast cancer samples, we found that some of the detected CNVs contained some genes that were related to breast cancer, such as PDZK1, XRCC4, Fbxl17, ITGBL1, RORA, BAGE, AMOTL1, RAP80, PIWIL4, CSE1L, and USP18." (PMID 34262604, 2021). "In order to further understand the role of PARP1, XRCC4 and ERCC1 in predicting the prognosis, metastasis of breast cancer, we also studied the best cut-off value of PARP1, XRCC4 and ERCC1." (PMID 33184404, 2020). "PARP1, XRCC4, ERCC1 is also found to be an independent factor for postoperative metastasis of breast cancer." (PMID 33184404, 2020). "So we combined protein expression (IHC score) of PARP1, XRCC4 and ERCC1 to detect the prognosis of breast cancer." (PMID 33184404, 2020). "The IHC scores of PARP1, XRCC4 and ERCC1 were higher than that of 6, 6 and 3 breast cancer metastasis, respectively." (PMID 33184404, 2020).
breast carcinoma (continued). "Nuclear proteins were extracted from the MCF7 breast cancer cell line and enrichment of NHEJ-related proteins including DNA-PKcs, Ku80, DNA ligase IV, and XRCC4 in the nuclear fraction compared with the cytosolic fraction was confirmed by immunoblotting." (PMID 29088817, 2017). "Immunofluorescence assays revealed abnormal expression of CTSL, CTSD, HSPA8, and XRCC4 in CD11b+ cells in tumor tissues than those in paracancerous normal tissues, regardless of breast cancer subtypes." (PMID 41399382, 2026). "In addition, Transwell results showed that silencing XRCC4 impaired the invasive capacities of MDA-MB-231 and MCF-7 breast cancer cells." (PMID 41399382, 2026). "So we combined PARP1, XRCC4 and ERCC1 to detect the prognosis of breast cancer." (PMID 33184404, 2020). "However, the mechanism of the effect of PARP1, XRCC4 and ERCC1 on the metastasis of breast cancer remains unclear, which needs further study (Fig. S1A1)." (PMID 33184404, 2020). "ER, HER2, E-Cad, Ki67, Molecular subtypes, XRCC1, XRCC4, 53BP1, ERCC1 and XPA were not independent prognostic factors of postoperative breast cancer metastasis (P > 0.05)." (PMID 33184404, 2020). "Conversely, some of the detected regions in the present work are not strongly related to breast cancer; recurrent losses affecting 7p22 (segment encompassing, among others, the PMS2 gene) and 5q11-q13 (ERCC8 and XRCC4) could suggest the involvement of DNA repair pathways in cancer progression." (PMID 25391423, 2015).